CDK7 (cyclin dependent kinase 7)
Diseases named in the same sentence as CDK7 in open-access papers (continued):
Sharing a sentence is not in itself a finding about the gene and the disease.
cancer (continued). "CDK7, an integral player within the general transcription factor TFIIH, exerts dual roles in cancer cell biology." (PMID 38037549, 2023). "CDK7 and CDK9 stand out as the most relevant targets, albeit through distinct mechanisms of oncogenicity and context-dependent contributions to cancer survival and drug sensitivity." (PMID 36577800, 2022). "In our study, we ectopically overexpressed MYC to mimic the dysregulated high MYC expression in cancer cells and investigated the sensitivity of high MYC-expressing cancer cells to CDK7 inhibition." (PMID 35406486, 2022). "Currently, the SE-related components recognized as cancer therapeutic targets are bromodomain containing 4 (BRD4), cyclin dependent kinase 7 (CDK7), E1A binding protein P300 (EP300), CDK8 and CDK19." (PMID 35303940, 2022). "Given the prevalence of super-enhancer dysregulation in cancer, inhibition of super-enhancer-driven gene expression has become a popular therapeutic strategy, with drugs targeting BRD4 and CDK7 being developed for anticancer therapies." (PMID 35563864, 2022). "We treated cSCC cells with THZ1, a covalent inhibitor of CDK7, and JQ1, a specific inhibitor of BRD4, which both have been shown to selectively target SE-driven transcriptional programs in cancer." (PMID 36010973, 2022). "Given the fact that CDK7 and CDK9 are more essential for cancer cell fitness relative to the other tCDKs, we focused on gene signatures enriched among their positive co-dependencies with potential oncogenic roles." (PMID 36577800, 2022). "Our studies indicate that targeting CDK7 serves as a new plausible strategy for treating HCC, in which MYC plays crucial roles in cancer cell proliferation and tumor growth." (PMID 35406486, 2022). "For instance, CDK7 inhibitors commonly repress MYC, an oncogene overexpressed in 70% of human cancers." (PMID 35757006, 2022). "The SMIs designed for the treatment of cancer include, for example, BRD4 inhibitor (JQ1) and CDK7 inhibitor (THZ1)." (PMID 36010973, 2022). "SNS-032, a novel and selective CDK7/9 inhibitor, that the first phase clinical trials approved by US FDA for cancer treatment have been completed." (PMID 35332847, 2022). "CDK20 also known as CCRK, which has sequence homology to CDK7, represents a novel cell cycle-related kinase (CAK) activity, and controls cell cycle progression in various cancers including lung, colorectal, liver and ovarian cancer." (PMID 33868579, 2021). "THZ1 is a potent CDK7 inhibitor that possesses an IC50 value of 3.2 nM for CDK7 and, also, inhibits CDK12 and CDK13 and shows antiproliferative activity on different cancer cell lines." (PMID 34885651, 2021). "The inhibition of CDK7 by THZ1 is related to the global transcriptional downregulation at high dose levels, but studies have found that cancer cell lines are sufficiently sensitive to lower doses of THZ1." (PMID 33299103, 2020). "Recently, inhibitors of CDK7, a subunit of the transcription factor complex TFIIH, were shown to disrupt SE networks in cancer cells and exert potent antitumor activity." (PMID 33168807, 2020). "As MYC TFs are frequently upregulated in cancer but have proven difficult to target directly, blocking MYC expression and/or targeting the transcription machinery downstream of MYC, by inhibiting CDK7, is an attractive strategy." (PMID 32385714, 2020). "Here, we show that dual treatment combining HER2-targeted therapy with the CDK7 inhibitor THZ1 strongly inhibits HER2+ BC cell growth and increases apoptosis in cancer cells that exhibit resistance to HER2-targeted therapies." (PMID 31462705, 2020). "CDK7 is also a master regulator of important genes in cancer, as it regulates MYC expression in many cancer types." (PMID 32340192, 2020). "Since upregulation of ABC-transporters is a common mechanism of cancer drug resistance, we used qRT-PCR to examine the mRNA levels of the most frequently observed transporters, ABCB1, ABCC1 and ABCG2, in our CDK7 inhibitor-resistant cell lines." (PMID 31530935, 2020).
cancer (continued). "Here we show that a CDK7 inhibitor, THZ1, strongly inhibited HER2+ BC cell growth and increased apoptosis, even in cancer cells that exhibited resistance to HER2-targeted therapy." (PMID 31462705, 2020). "Although targeting CDK7 effectively inhibited the growth of human malignancies, THZ1 has antitumor effects on several human cancers." (PMID 31752390, 2019). "By using BET inhibitor, CDK7 inhibitor, AKT inhibitors, demethylases, and acetyltransferase, researchers target carcinogenic SEs to inhibit cancer growth, invasion, immune escape and progression." (PMID 31824865, 2019). "To test this idea, we recently performed super-enhancer profiling in one of the most intractable cancers, adult T-cell leukemia (ATL), and tested the therapeutic efficacy of CDK7 inhibitors in this disease." (PMID 29724031, 2018). "The CDK7 inhibitor THZ1 and BRD4 inhibitor JQ1 can efficiently target MYC driven transcriptional amplification in other types of cancers, here we studied the potential role of THZ1 and JQ1 in regulation of ostesosarcoma." (PMID 29644114, 2018). "A list of significant biomarkers for cancer was generated like CDH2 and CDK7, and functional enrichment analysis identified the role of miRNAs in major pathways like cell adhesion molecules pathway affected by cancer." (PMID 29516011, 2018). "Cyclin-dependent kinase 7 (CDK7), which promotes transcription during the cell cycle, is critical for the survival of cancer cells." (PMID 28210221, 2017). "Recent studies using a novel Cdk7 specific covalent inhibitor, THZ1, revealed important roles of Cdk7 in transcription regulation in cancer cells." (PMID 29163040, 2017). "Transcription-regulating kinases CDK7, CDK9 and CDK8/19 have become actively pursued targets in cancer therapy, due in part to their effects on super-enhancers that develop during carcinogenesis and become essential for the survival of tumor cells." (PMID 28147342, 2017). "CDK7 and CDK9 are targeted by flavopiridol (DB03496), which is a cancer drug treating various types of cancer." (PMID 27801815, 2016). "The relevance of CDK2, CDK7, and/ or CDK9 as crucial SNS-032 drug targets differs between different cancer cell types." (PMID 27517323, 2016). "The recently identified CDK9-targeted kinases, CDK7, CDK2, and phosphatases, PP1, and PPM1A will likely emerge as novel targets for anti-HIV-1 and cancer therapeutics." (PMID 24524087, 2014). "Interestingly, on the examined cancer cell lines, they demonstrated potential as dual inhibitors of JAK1 and CDK7." (PMID 41530217, 2026). "More precise and better-tolerated inhibitors targeting CDK7 and CDK12 are necessary in order to gain a complete understanding of the potential of these kinases as therapeutic targets in GBM, as well as other types of cancer." (PMID 40996961, 2025). "Increased growth signaling makes cancer cells, but not normal healthy cells, more sensitive to CDK7 inhibitors." (PMID 40149983, 2025). "It inhibited CDK7 in the CAK and TFIIH complexes, leading to reduced transcription in tumor cells, G2/M cell cycle arrest, downregulation of key oncogenes like c-MYC, and ultimately inducing apoptosis in cancer cells." (PMID 40949156, 2025). "Some CDK7 inhibitors, such as THZ1, could function as efficient drugs to control cancer cell proliferation or death." (PMID 38640110, 2024). "Specifically, CDK7 interacts with C-terminal binding protein 2 (CtBP2), a protein known to promote tumor progression by enhancing epithelial-mesenchymal transition (EMT) and inhibiting apoptosis in cancer cells." (PMID 38605321, 2024). "Notably, multiple CDK7 inhibitor drugs (CT7001 and SY‐1365) have entered early‐phase clinical trials for cancer treatment." (PMID 39492805, 2024). "To further clarify the therapeutic potential of CDK7 in treating GBC, we evaluated the effects of another two selective CDK7 inhibitors, SY‐1365 and CT7001, both of which have entered human clinical trials for cancer treatment." (PMID 39492805, 2024).
cancer (continued). "Furthermore, CDK7 and BET‐Bromodomain inhibitors have exhibited anti‐tumor efficacy by targeting MYCN in various cancers." (PMID 39248163, 2024). "In addition, studies have shown that the inhibitors of CDK7(THZ1) or CDK9(CYC065) can disrupt abnormal MYCN-driven transcription and inhibit MYCN gene transcription, becoming potential anti-cancer drugs." (PMID 36770809, 2023). "Targeting cysteine residues outside the ATP‐binding cassette of CDK7 is a novel approach for developing CDK7is,22 enabling selective repression of CDK7 kinase activity, RNAPOLII CTD phosphorylation, SE activity and gene transcription, culminating in cancer cell death." (PMID 38037549, 2023). "This could indicate that CDK7 and CDK9 contribute to cancer cell fitness through regulation of different aspects of the MYC transcriptional network." (PMID 36577800, 2022). "For example, whereas loss of CDK9 produces responses in cancer cells that resemble the loss of key components of the transcriptional machinery (e.g., RNAPII subunits), this is not the case for CDK7." (PMID 36577800, 2022). "It has been shown that Nic induces downregulation of CDK2 and CDK4, but not CDK7, cyclin D2 or cyclin H in other cancer types." (PMID 36304150, 2022). "CDK7 inhibitors are being investigated as anti-cancer drugs, and CDK12/13 inhibitors are used in the treatment of a variety of cancers." (PMID 36299580, 2022). "There is a growing body of evidence suggesting that other cyclin-dependent kinases including CDK7, CDK8, CDK9, and CDK12 may also be important for modulating the sensitivity of cancer cells to the effects of ionizing radiation." (PMID 34932500, 2022). "Thus, CDK7 and CDK12/13 inhibitors likely modulate similar biological processes through different mechanisms, suggesting possible synergistic anti‐cancer effects on their combined administration." (PMID 34092037, 2021). "In addition, CDK7/9 phosphorylate serine 256 of OGFOD1, which promotes its driving ability in cancer both in vitro and in vivo." (PMID 34298635, 2021). "Preclinical studies have confirmed that covalent CDK7 inhibitors selectively induce apoptosis in certain cancers, but not in normal human cells." (PMID 34109118, 2021). "Importantly, overexpression of the CDK7 C312S mutant renders cancer cell lines resistant to many of the effects of THZ1, confirming its specificity for CDK7 in cells." (PMID 32397434, 2020). "BRD4 and CDK7 inhibitors JQ1 and THZ1 can kill many different cancer cells." (PMID 33298918, 2020). "The CDK7 inhibitors (CDK7i) ICEC0942 and THZ1, are promising new cancer therapeutics." (PMID 31530935, 2020). "Additionally, we showed that CDK7 inhibition reactivated immunity by suppressing p38α/MYC/PD-L1 and sensitized cancer cells to anti-PD1 therapy in vivo, which indicated CDK7 as an attractive target for epigenetic therapy of NSCLC." (PMID 32690037, 2020). "Because p38α has been reported as a promising therapeutic target in many cancers including NSCLC, we test if inhibition of CDK7 and p38α could enhance antitumor effects in synergy." (PMID 32690037, 2020). "Since BET proteins, CDK7, CDK9, and HDACs, serve as actionable targets in many cancers addicted to CRC, combination of CRC-disrupting agents with either current treatment modalities or novel antitumor compounds may improve therapeutic response." (PMID 32943730, 2020). "A number of covalent CDK7 inhibitors have also been developed, the first being THZ1, which targets a cysteine residue (Cys312) on a C-terminal extension just outside the ATP-binding site of CDK7 and has strong activity in many cancer types." (PMID 32385714, 2020). "In summary, our data identify CDK7 as a new therapeutic target to improve the treatment and survival of patients with HER2+ BC and reveal how CDK7 acts as a transcriptional kinase in these cancers." (PMID 31462705, 2020).
cancer (continued). "Furthermore, substances that specifically inhibit the kinase activity of Cdk7 have been developed; one of these drugs is THZ1, which, together with triptolide, has promising prospects for use against cancer." (PMID 31963603, 2020). "Cancer cells are more sensitive to treatment with small-molecule inhibitors of CDK7 or BRD4 than non-transformed cells." (PMID 29724031, 2018). "Genomic alterations in CDK7 have not been widely reported in cancer." (PMID 39800748, 2025). "Similarly to CDK9, CDK7 also has a bidirectional relationship with BRD4 whereby both are substrates for each other, creating a regulatory loop that is important for gene transcription in cancer." (PMID 40163908, 2025). "Consequently, the targeting of transcription regulators like CDK7 has emerged as a strategy to dismantle this transcription boost, with THZ1 and THZ2 showing particular efficacy against cancers that rely on SE-driven genes including C-MYC, RUNX2, STAT, SOX2, MITF, SOX9." (PMID 38605321, 2024). "It has been reported that THZ1, a specific inhibitor of CDK7 to block the phosphorylation of the CDK7 substrate RNAPII CTD by irreversible covalent binding to CDK7, can negatively affect gene expression, inhibiting the proliferation of cancer cells and the progression of animal xenograft models." (PMID 38540292, 2024). "As elimination of cancer cell by irreversible cell death is a desirable outcome of any effective cancer treatment, we examined whether the targeting of CDK12 or P-TEFb switches the fate of CDK7-inhibited cells from cell-cycle arrest to apoptosis." (PMID 37811895, 2023). "Indeed, recent work demonstrated that targeting CDK7, P-TEFb, and CDK12/13 with potent small-molecule inhibitors could lead to vigorous anti-tumor effects in xenograft and pre-clinical models of cancer." (PMID 36727434, 2023). "Moreover, selective inhibition and knockdown of cyclin-dependent kinase 7 (CDK7) as well as knockdown of its phosphorylation target the MED1 subunit of the Mediator complex induce both NEAT1_2 splicing and read-through transcription in cancer cell lines." (PMID 36279270, 2022). "This could imply that the dependence of cancer cells on CDK7 may not be primarily due to its transcription-related activities." (PMID 36577800, 2022). "CDK7 might also be an attractive target in MYC‐driven tumors: indeed, the covalent CDK7 inhibitor THZ1 disproportionally repressed super‐enhancer regulated genes, including MYC, MYCN and MYCL in diverse cancer‐derived cell lines." (PMID 36214609, 2022). "Collectively, these observations suggest that while cancer cells respond similarly, in terms of cell viability in vitro, to the loss of CDK9 and key factors controlling transcription, this is not the case for the majority of tCDKs, including CDK7." (PMID 36577800, 2022). "Therefore, MYC-driven cancers, including TNBC, are more sensitive to CDK7 inhibition." (PMID 36139513, 2022). "Importantly, RA, inhibitors of HDACs, BET bromodomain containing proteins, CDK7, CDK9 and small molecules that bind to G4s have been demonstrated to be effective for the treatment of many types of cancers by targeting their dysregulated transcriptional programs." (PMID 33628735, 2020). "Therefore, whereas both CDK7 and CDK9 may contribute to cancer cell fitness through differential interactions with the MYC network, they display clearly specialized relationships with other signaling pathways relevant for cancer development." (PMID 36577800, 2022). "Therefore, targeting CDK7 may provide an alternative therapeutic option to block the reactivation of receptor tyrosine kinase pathways in RTK-driven neoplasms, especially for TKI-resistant cancer." (PMID 36076237, 2022). "We found that tCDKs have a wide range of effects on cancer cell viability, with CDK7 and CDK9 being the most essential across different cancer lineages, while other tCDKs display context-dependent essentiality that is independent of cancer type." (PMID 36577800, 2022).
cancer (continued). "Cyclin-dependent kinase 7 (CDK7) is crucial for cell cycle progression and gene expression transcriptional regulation, which are often not assessed in cancer developing process." (PMID 34109118, 2021). "They found that CDK7 inhibition blocked the glycolysis pathway without affecting glutamine metabolism, suggesting that the inhibitory effect of THZ1 is due in part to an impairment of cancer metabolism." (PMID 36212402, 2022).